SDC1 (syndecan 1)
Diseases named in the same sentence as SDC1 in open-access papers (continued):
Sharing a sentence is not in itself a finding about the gene and the disease.
psoriasis (5 papers, 2021 to 2025). An autoimmune condition characterized by red, well-delineated plaques with silvery scales that are usually on the extensor surfaces and scalp. "Absence of syndecan-1 correlates with an increased inflammatory response in models of psoriasis, and this is linked to the elevated levels of a subset non-SDC1 expressing γδ T cells." (PMID 33561383, 2021). "Consequently, we can speculate that syndecans may be implicated in cell signaling or be affected by FN in psoriasis, too, at least for syndecan-1 according to our data." (PMID 35742957, 2022). "In this study, we looked for evidence implicating the syndecan-1 and syndecan-4 expressed within the human epidermis with the pathogenesis of psoriasis." (PMID 35742957, 2022). "Previous data show that the heparan sulfate proteoglycan syndecan-1 plays a critical role in modulating psoriasis-like skin inflammation in mice." (PMID 34715781, 2021). "Heparan sulfate proteoglycan syndecan-1 (SYND1) plays a critical role in regulating psoriasis-like skin inflammation in mice." (PMID 34715781, 2021). "Our study provides evidence for the involvement of syndecan-1 and/or syndecan-4 in the pathogenesis of psoriasis and could serve as potential targets for treatment." (PMID 35742957, 2022). "Here, syndecan-1 and -4 were examined in lesional skin of patients with psoriasis." (PMID 35742957, 2022). "The significant increase in the expression of heparanase-1 (HPSE), heparanase-2 (HPSE2), syndecan-1 (SYND1), metalloproteinase-9 (MMP9), and tissue inhibitor of metalloproteinase 2 (TIMP2) in biopsies of skin affected by psoriasis showed extracellular matrix alterations in psoriasis." (PMID 34715781, 2021). "The protein expression of the heparan sulfate proteoglycan, syndecan-1, is significantly higher in the non-affected skin samples from patients with psoriasis than skin tissue collected from psoriasis plaque 173.08 ± 7.93 ou/μm2 versus 150.34 ± 17.44 ou/μm2 (p = 0.0093)." (PMID 34715781, 2021).
septic shock (5 papers, 2011 to 2025). Shock caused by infection; frequently caused by gram negative bacteria, although some cases have been caused by other bacteria, viruses, fungi, and protozoa; characterized by fever, chills, tachycardia, tachypnea, and hypotension. "Previously, in a septic shock experimental model, plasma reduced syndecan-1 levels and improved mortality compared to the use of a threefold higher volume of crystalloids." (PMID 39999161, 2025). "The purpose of this study is to investigate the time course of syndecan-1 (Syn-1) plasma levels, the correlation between Syn-1 and organ damage development, and the associations of Syn-1 level with cumulative fluid balance and ventilator-free days (VFD) in patients with septic shock." (PMID 33726863, 2021).
squamous cell lung carcinoma (5 papers, 2015 to 2025). A carcinoma arising from squamous bronchial epithelial cells. "In squamous cell lung carcinoma low cell surface syndecan-1 expression is associated with unfavorable outcome and the majority of NSCLC express varying syndecan-1 reactivity by immunohistochemistry of tumor tissue." (PMID 26420915, 2015). "Cancers with high SDC1 expression were associated with more favorable overall survival, suggesting that loss of SDC1 expression occurs as a result of histological dedifferentiation and that low SDC1 expression is associated with unfavorable outcomes in squamous cell carcinoma of the lung." (PMID 26293675, 2015). "In another study, evaluation of SDC1 expression in squamous cell lung carcinoma patients showed higher expression of SDC1 in well-differentiated cancers than in moderately or poorly differentiated tumors." (PMID 26293675, 2015).
bladder tumor (4 papers, 2014 to 2019). "Other investigators have reported a positive correlation of SDC-1 with fibroblast growth factors (FGFRs) in bladder tumors, these factors are thought to be key molecules in low-grade BCa." (PMID 24524203, 2014). "In their study, the BCa cell lines, UMUC2 and UMUC3 had SDC-1 expression silenced by siRNA transfection, which led to an induction of apoptosis in vitro and a reduction in mouse orthotopic bladder tumor growth." (PMID 24524203, 2014). "Further studies are underway to understand the role of SDC-1 in BCa and to investigate the prognostic potential of SDC-1 monitoring in human bladder tumors." (PMID 24524203, 2014). "Evaluation of urinary levels of SDC1 in urinary bladder tumors may also be considered during the assessment of tumor severity." (PMID 26293675, 2015). "In summary, decreased urinary levels of SDC-1 in BCa patients were associated with high-grade or high-stage disease, and this phenomenon correlated with a shift of SDC-1 protein cellular localization from the cellular membrane to the cytoplasm in these high-grade and high stage bladder tumors." (PMID 24524203, 2014). "Within bladder tumors, 55% of high-grade tumors (compared to low-grade tumors, p < 0.0001) were noted to have increased cytoplasmic expression and reduced membranous expression of SDC-1." (PMID 24524203, 2014). "We used two complimentary approaches to classify SDC-1 expression in human bladder tumors." (PMID 24524203, 2014). "Though a difference in SDC-1 expression pattern was not seen between bladder tumors and benign bladder histology, possibly due to the small sample size of the benign cohort, a significant shift in cellular localization of SDC-1 was associated with high-grade tumors and MIBC." (PMID 24524203, 2014). "We did not observe this phenomenon in our study, the majority of SDC-1 expression was in the epithelial component of the bladder tumors." (PMID 24524203, 2014).
cholangiocarcinoma (4 papers, 2015 to 2023). A carcinoma that arises from the intrahepatic biliary tree (intrahepatic cholangiocarcinoma) or from the junction, or adjacent to the junction, of the right and left hepatic ducts (hilar cholangiocarcinoma). "Only one other study, conducted by Harada and coauthors (2003), had previously addressed the question as to whether syndecan-1 is associated with patient prognosis in cholangiocarcinoma." (PMID 34206469, 2021). "These concordant findings underline the importance of further studies regarding the role of syndecan-1 in cholangiocarcinoma." (PMID 34206469, 2021). "In our series, syndecan-1 staining intensity was significantly lower in cholangiocarcinoma when compared to normal bile ducts." (PMID 34206469, 2021). "To investigate syndecan-1 in cholangiocarcinoma, we performed immunohistochemical analyses using our large cohort of over 470 iCCA, PHCC, dCCA, and GBC." (PMID 34206469, 2021). "This is the first study to comprehensively study syndecan-1 in cholangiocarcinoma to unravel its possible role as a therapeutic agent, as already shown for PDAC." (PMID 34206469, 2021). "In cancerous tissues, the distribution of SDC1 mRNA was similar to that of the protein, suggesting that SDC1 expression in intrahepatic cholangiocarcinoma is regulated at the transcriptional level." (PMID 26293675, 2015). "We therefore aimed to investigate the role of syndecan-1 in cholangiocarcinoma." (PMID 34206469, 2021). "For this reason, to reliably compare cholangiocarcinoma and PDAC, two subgroups may be needed to further depict an independent role of syndecan-1, namely, KRAS-mutated and KRAS-wildtype tumors." (PMID 34206469, 2021). "Further experimental investigations are therefore needed to clarify whether syndecan-1 may predict chemotherapy response in cholangiocarcinoma and whether macropinocytosis may be involved in cholangiocarcinoma progression." (PMID 34206469, 2021). "We aimed to elaborate whether syndecan-1 expression correlates to survival in cholangiocarcinoma and thereby parallels its function in PDAC." (PMID 34206469, 2021). "In intrahepatic cholangiocarcinoma, syndecan-1 H-score had no significant influence on recurrence-free survival, although KRAS-mutation status had an influence on recurrence-free survival in cholangiocarcinoma of the cBioPortal cholangiocarcinoma cohort." (PMID 34206469, 2021). "To conclude, we could not show an impact of syndecan-1 on patient prognosis in cholangiocarcinoma, at least none that could be shown immunohistochemically." (PMID 34206469, 2021).
corneal infection (4 papers, 2014 to 2023). A viral or bacterial infectious process affecting the cornea. "Sdc1 knockout is a gain-of-function mutation in S. pneumoniae corneal infection." (PMID 33293379, 2020). "We found that deletion of syndecan-1 (Sdc1), a major cell surface HSPG of epithelial cells, causes a gain of function in a mouse model of scarified corneal infection, where Sdc1−/− corneas were significantly less susceptible to Streptococcus pneumoniae infection." (PMID 33293379, 2020). "Instead, the hyposusceptible phenotype of syndecan-1 knockout mice in S. pneumoniae corneal infection was traced to a marked reduction of FN fibrils in the corneal basement membrane that serve as S. pneumoniae attachment sites." (PMID 38957622, 2023). "We recently examined if S. pneumoniae binds to syndecan-1 and uses this interaction for its corneal infection because syndecan-1 is the major HSPG of epithelial cells, a cell type frequently targeted for pathogenesis." (PMID 38957622, 2023). "Altogether, these data suggest that Sdc1 is a host factor that prominently and specifically promotes S. pneumoniae corneal infection." (PMID 33293379, 2020). "Based on the expression pattern of syndecans in the cornea, we next carried out experiments to determine if Sdc1 and Sdc4 modulate the pathogenesis of S. pneumoniae corneal infection." (PMID 33293379, 2020). "We thus pursued the possibility that Sdc1 ectodomains inhibit S. pneumoniae corneal infection by interfering with bacterial binding to other HSPGs in Wt corneas and that these HSPG receptors are absent or expressed in reduced amounts in Sdc1−/− corneas." (PMID 33293379, 2020). "We serendipitously discovered that epithelial Sdc1 facilitates the assembly of FN fibrils in the corneal basement membrane and that this normal biological function of Sdc1 has detrimental consequences for the host in S. pneumoniae corneal infection." (PMID 33293379, 2020). "Excess Sdc1 ectodomains inhibited S. pneumoniae corneal infection by binding to the Hep II domain and interfering with S. pneumoniae PavA binding to FN." (PMID 33293379, 2020). "S. aureus induced syndecan-1 shedding from the corneal surface and syndecan-1 null mice significantly resisted S. aureus corneal infection compared with wild-type animals." (PMID 25184228, 2014).
esophageal cancer (4 papers, 2021 to 2025). A primary or metastatic malignant neoplasm involving the esophagus. "Loss of syndecan-1 expression in most epithelial tumors such as cervical, lung, head and neck, squamous cell, and esophageal cancers is associated with tumor progression and reduced patient survival, suggestive of a tumor suppressive role for syndecan-1." (PMID 36693448, 2023). "This might allude to the elevation of Syndecan-1 levels in patients with esophageal cancer even without surgery, as we already detected in patients with cancers of the oral cavity." (PMID 40943808, 2025).
fibrosis (4 papers, 2016 to 2022). the formation of excess fibrous connective tissue in an organ or tissue in a reparative or reactive process. "In contrast, through TGFβ1-binding, thus enhancing its clearance, overexpression of soluble syndecan-1 is highly associated with fibrosis, either myocardial or hepatic, extensive evidence being provided by several studies." (PMID 31815014, 2019). "SDC-1 is known for its function in the cardiac fibrosis, and our analyses found SDC-1 in close interaction with AF-associated genes, e.g., SELE." (PMID 36078037, 2022). "Similar results were obtained in co-culture assays using lung epithelial cells with F-EVs from mice that were WT and with Sdc1−/− BLM-fibrosis." (PMID 36232350, 2022).
head and neck squamous cell carcinoma (4 papers, 2017 to 2025). A squamous cell carcinoma that arises from any of the following anatomic sites: lip and oral cavity, nasal cavity, paranasal sinuses, pharynx, larynx, and salivary glands. "For example, head and neck squamous cell carcinoma (HNSCC) cells expressing high levels of SDC1 migrated poorly and are less invasive in collagen I matrices as compared to HNSCC cells expressing lower levels of SDC1." (PMID 29230082, 2017).
Hodgkins lymphoma (4 papers, 2012 to 2024). A heterogeneous group of malignant lymphoid neoplasms of B-cell origin characterized histologically by the presence of Hodgkin and Reed-Sternberg (HRS) cells in the vast majority of cases. "FGF2 and SDC1 overexpression by circulating CD15+/CD 30+ cells is associated with poor outcome in Hodgkin Lymphoma." (PMID 23988031, 2013). "Further, Reed Sternberg cells in classical Hodgkin disease express syndecan-1, whereas the putative tumor cells of nodular lymphocyte predominant subtype of Hodgkin disease do not." (PMID 22777011, 2012).
Hypervolemia (4 papers, 2021). An increase in the amount of intravascular fluid, particularly in the volume of the circulating blood. "Previous studies have reported an association between hypervolemia from rapid fluid administration and glycocalyx shedding as measured by syndecan-1." (PMID 33402229, 2021).
Kawasaki disease (4 papers, 2020 to 2025). A rare inflammatory disease characterized by an acute febrile, systemic, self-limiting, medium-vessel vasculitis primarily affecting children. "Serum levels of soluble syndecan-1, one of the major core proteins expressed in the VEGLX, are thought to reflect vascular endothelial damage and inflammation in Kawasaki disease." (PMID 33352699, 2020).
kidney (4 papers, 2013 to 2025). "In kidney transplant patients and animal models, increased tubular Sdc-1 expression was suggested to promote tubular survival and repair, while increased Sdc-1 plasma levels reflected early loss of tubular function." (PMID 32701966, 2020). "For urogenital cancers, high local or systemic concentrations of Syndecan-1 have been shown." (PMID 40943808, 2025).
liver cirrhosis (4 papers, 2020 to 2024). "Liver cirrhosis is characterized by increased amounts of syndecan-1, and shed syndecan-1 has been experimentally shown to protect against fibrotic remodeling." (PMID 32977498, 2020).
malignant glioma (4 papers, 2012 to 2023). A grade III or grade IV glioma arising from the central nervous system. "The interaction between THBS1 and SDC1 expressed in malignant gliomas promotes tumor cell invasion." (PMID 37905960, 2023).
metastatic melanoma (4 papers, 2015 to 2025). A melanoma that has spread from its primary site to another anatomic site. "SDC1, a cell surface heparan sulphate proteoglycan, promotes canonical Wnt signalling in metastatic melanoma." (PMID 30566430, 2018). "In conclusion, these findings indicate for the first time the involvement of Syndecan-1 in the process of VM in metastatic melanoma." (PMID 26460958, 2015). "In human metastatic melanoma biopsies obtained from different patients the same co-localization of Syndecan-1 with CD144 or VEGFR-2 was observed." (PMID 26460958, 2015). "Blocking Syndecan-1 activity by OC-46F2 antibody in combination therapy with L19-IL2 could result in potential novel therapeutic approaches for metastatic melanoma." (PMID 26460958, 2015).
osteoarthritis (4 papers, 2022 to 2025). A noninflammatory degenerative joint disease occurring chiefly in older persons, characterized by degeneration of the articular cartilage, hypertrophy of bone at the margins and changes in the synovial membrane. "Moreover, an increased expression of some of the HS core proteins in osteoarthritis, including perlecan, syndecan 1, or syndecan 4 has been shown." (PMID 38136608, 2023).
pancreatic ductal adenocarcinoma (4 papers, 2021 to 2023). An infiltrating adenocarcinoma that arises from the epithelial cells of the pancreas. "Syndecan-1 was recently uncovered to be upregulated at the cell surface by KRAS in pancreatic ductal adenocarcinoma (PDAC)." (PMID 34206469, 2021). "In some gastrointestinal tumors, e.g., hepatocellular carcinoma and pancreatic ductal adenocarcinoma, levels of syndecan-1 can be increased." (PMID 33921767, 2021). "Membrane localization of trafficking syndecan-1 (SDC1) has been shown to be an essential mechanism for promoting macropinocytosis and sustaining the uncontrolled growth of oncogenic KRAS-driven pancreatic ductal adenocarcinoma (PDAC)." (PMID 36046825, 2022). "In pancreatic ductal adenocarcinoma (PDAC), serum SDC1 level was remarkably elevated, and receiver operating characteristic (ROC) analysis area under the curve was 0.847, suggesting that serum SDC1 served as a promising novel biomarker for PDAC early diagnosis." (PMID 37950222, 2023).
peritonitis (4 papers, 2012 to 2023). Inflammation of the peritoneum (tissue that lines the abdominal wall and covers most of the organs in the abdomen). "Plasma concentration of Syndecan 1 was comparable in the two groups at 6 h of peritonitis 0.6 ± 0.2 ng/ml vs 0.5 ± 0.2 ng/ml (p = 0.292)." (PMID 37733256, 2023). "Given that S. aureus and P. aeruginosa are common pathogens that induce peritonitis in PD patients, it is possible that both microorganisms implement the shedding of syndecan-1 ectodomain from the mesothelium to promote their pathogenesis during peritonitis." (PMID 22577250, 2012). "We did, however, find that syndecan-1 is important for limiting acute peritoneal S. aureus infection, which may have implications for incidence of peritonitis and infections in PD patients." (PMID 26832929, 2016). "Because inflammation was shown to alter syndecan-1 levels in tissues, the level of syndecan-1 was measured in LTA-induced peritonitis and saline-injected controls." (PMID 25184228, 2014). "Thus, perhaps we didn't observe significant syndecan-1 shedding in this model of LTA-induced peritonitis because of the absence of certain staphylococcal toxins." (PMID 25184228, 2014).
Shock (4 papers, 2011 to 2022). The state in which profound and widespread reduction of effective tissue perfusion leads first to reversible, and then if prolonged, to irreversible cellular injury. "In conclusion, this study demonstrates Sdc1 to be a novel target of endothelial cell miR-19b after hemorrhagic shock." (PMID 32978505, 2020). "We have shown similar findings of syndecan-1 preservation by FFP after in vitro treatment of cells with heparanase, a syndecan-1 shedding enhancer and in animals after hemorrhagic shock." (PMID 21886795, 2011). "Sdc1 ectodomain is shed following a multitude of insults including hemorrhagic shock and sepsis." (PMID 32978505, 2020).